SMAD7 (SMAD family member 7)
Diseases named in the same sentence as SMAD7 in open-access papers (continued):
Sharing a sentence is not in itself a finding about the gene and the disease.
tumor (continued). "Smad7-dependent activation of TGFβ signaling is able to induce the epithelial to mesenchymal transition (EMT) in CRC, allowing CRC cells to leave the tissue parenchyma and enter systemic circulation, followed by tumor invasion and metastasis." (PMID 28095858, 2017). "Previous studies showed that miR-195 could bind to Smad7 and its target site was located within 1611 and 1630 nt of Smad7 mRNA 3′-UTR and miR-195 was possibly a tumor promoter in U87 cells by targeting Smad7." (PMID 28929107, 2017). "Although we did not observe obvious differences of SMAD7 mRNA levels in the tumours expressing high or low levels of miR-182, the SMAD7 protein level was significantly lower in the samples with abundant miR-182." (PMID 27996004, 2016). "Moreover, adoptive transfer of CD4+ T cells overexpressing Smad7, an intracellular inhibitor of TGF-β signaling, resulted in increased number of tumor-infiltrating Th17/Th1 hybrid cells and inhibition of tumor growth." (PMID 26583099, 2015). "The efficacy mechanisms may involve in reinforcing immune responses, increasing expression of miR200c, E-cadherin and SMAD-7 and decreasing expression of TGF-β, ZEB1, Vimentin and N-cadherin in tumor tissues from the immunized mice." (PMID 24625224, 2014). "Our data strongly suggest that the shift between tumor suppressive and tumor promoting TGF-β effects involves different regulation of Smad3 dependent transcription, TβRI expression, Smad2 signaling duration, and endogenous TGF-β/Smad7/TβRII levels." (PMID 23991075, 2013). "Smad7 overexpression has previously been shown to decrease COL1A1 mRNA levels in normal human fibroblasts, which supports our results obtained in fibroblasts directly co-cultured with tumour cells." (PMID 24090133, 2013). "In particular, downregulation of TGFβ receptors, Smad7, MMPs, cyclin D1, and NF-κB by chlorophyllin and ellagic acid may play a key role in impeding the development of HBP tumours." (PMID 22485181, 2012). "Absent/low Smad7 protein expression showed a significant positive correlation with tumour size (r = 0.421, p < .036) and margin status (r = 0.431; p < .032)." (PMID 22195733, 2011). "When clinical-pathological features as lymph node status, tumor size, differentiation degree, pathological staging, age, gender and smoking degree were considered, no statistical difference was found related to Smad7 status." (PMID 20462450, 2010). "Indeed, several of the identified genes in our study are reported to be involved in angiogenesis, tumor angiogenesis and arteriogenesis, i.e. IL-8, ET-1, CARP, HPTPη, ID1, MGSA, SMAD7, HO-1, RHOB, PTHLH, SERPINH1/HSP47, JAG1, GNA13 and TEAD4." (PMID 16594992, 2006). "In contrast, the tumor-specific cluster C3 appears less differentiated with features typical of CD56brightCD16neg NK cells (NCAM1, CD2, CD27, SELL, CD69) as well as a signature of tissue residency (CD69 and ITGA1) and of TGF-β-induced genes (SMAD7, TGFB1, PMEP1, SKIL)." (PMID 41145419, 2025). "Using resin-assisted capture and metabolic labeling methods, we show here that Smad7 is S-palmitoylated in mammary epithelial cell models that are widely studied because of their strong responses to TGF-β and their biological relevance to mammary development and tumor progression." (PMID 38876303, 2024). "Hence, high expression of Smad7 and low expression of TGFβR1 in HCC tumors and surrounding normal liver tissues could be tumor suppressive." (PMID 34323416, 2021). "For example, Smad7 retains the NF-κB inhibitor alpha (IκBα) expression; inhibits NF-κB-activated genes such as tumour necrosis factor alpha (TNFα), interleukin 1 beta (IL1β), and intercellular adhesion molecule 1 (ICAM1); and thereafter plays an anti-inflammatory role in several tumour cell lines." (PMID 33282009, 2020). "Notably, overexpression of Smad7 in Ikkβ-deficient fibroblasts prevented HGF secretion thus confirming the tumor-suppressor role of Smad7 expressed by non-epithelial cells." (PMID 31052449, 2019).
tumor (continued). "Indeed, subcutaneous delivery of SMAD7-expressing cells derived from non-tumorigenic human colon adenocarcinoma promoted tumor growth in nude mice, whereas control vector cells failed to form tumors." (PMID 29799477, 2018). "Interestingly, Smad7 was not generally upregulated or downregulated in tumor or surrounding tissue areas, but the expression was found to be high as well as low both in tumor as well as non-tumor tissue of different animals." (PMID 28134936, 2017). "In addition, our data demonstrated the aberrant up-regulation of miR-182 and its negative correlation with SMAD7 protein in tumours samples." (PMID 27996004, 2016). "Moreover, we identified Smad7 as a putative negative regulator of both CCN2 and type I collagen gene expression in fibroblasts, with Smad7 mRNA and protein levels being significantly increased in CCD-1068SK fibroblasts that were directly co-cultured with MDA-MB-231 tumour cells." (PMID 24090133, 2013). "In another study, primary mouse keratinocytes were transduced with the Smad7 gene resulting in enhanced keratinocyte proliferation, blocked normal differentiation, and induced keratin 8, a marker of malignant conversion, but did not result in tumor formation." (PMID 24047375, 2013). "Since fibroblasts directly co-cultured with tumour cells were found to have elevated Smad7 gene expression with downstream effects on CCN2 and type I collagen, we therefore asked whether Smad7 affects activation of the ERK signalling pathway." (PMID 24090133, 2013). "In addition, in mRNA levels, the relations between TGF β1 and Smad2, Smad7 were also found (R2=0.12, P=0.059 and R2=0.40, P<0.001, respectively), but none of them correlated to tumor size." (PMID 23151305, 2012). "Except for the changes of tumor incidence, there appeared no discernable difference in the structural property of the tumor as histological analysis revealed the same type of adenocarcinoma in both the wide type and Smad7 transgenic mice." (PMID 20405019, 2010). "Diffuse positive Ki67 (a cell proliferation marker) staining was detected in Smad7-mediated liver metastases, as compared to livers from parental FET and vector control cells, suggesting the involvement of increased cell proliferation in metastatic tumour growth." (PMID 18781153, 2008). "The effects of TAZ on TNBC tumour progression, including also modulation of the immune TME, might therefore be modulated in part via interactions not only with TEADs but also with other transcription factors such as SMAD2/3 or SMAD7, which regulates Treg migration into tumours." (PMID 37716913, 2023). "The correlation coefficient between USP15 and SMAD7 (R = 0.11, p < 0.05) The Smad protein is the first detected kinase substrate of the TGF-β receptor, so we hypothesize that USP15 in BRCA most likely plays a role in promoting tumor development and metastasis via the TGF-β/smad signaling pathway." (PMID 36213818, 2022). "If regulatory control of SMAD7 is missing at this stage, TGF-β exhibits increased tumor-promotive functions such as epithelial-to-mesenchymal transition, migration and invasion and the activation of tumor-promotive STAT3 signaling could further accelerate the vicious development." (PMID 28134936, 2017). "In line with the expectation that cell types of the microenvironment such as macrophages rather than hepatocytes or tumor cells mainly produce IL-6, we could not find a significant effect of SMAD7 overexpression on the production of Il-6 mRNA or secretion of IL-6 in HuH-7 cells." (PMID 28134936, 2017). "Analogously, the DNA methylation level of SMAD7 was markedly increased in LAD tissues as compared to the normal lung tissues and negatively correlated with SMAD7 mRNA levels in our collected tumor tissue cohort." (PMID 37072414, 2023).
tumor (continued). "All patients with SMAD7 T/N ratios <1 showed strong pSMAD2 positivity in the tumors, suggesting enhanced TGF-β signaling in tumors with low SMAD7 levels, while STAT3 signaling was only activated in three patients and not all tumor cells." (PMID 28134936, 2017). "The upstream events leading to Smad7 overexpression in the herein described direct co-culture model of CCD-1068SK fibroblasts and MDA-MB-231 tumour cells has not yet been determined." (PMID 24090133, 2013). "Analysis of gene expression by quantitative real-time RT-PCR in indirectly co-cultured CCD-1068SK fibroblasts revealed that tumour cells did not influence the expression of COL1A1, COL1A2, CCN2 or Smad7 when compared to fibroblast monocultures." (PMID 24090133, 2013). "miR-181a could act as a tumour suppressor in paediatric ALL by over-expressing its target, small mother against decapentaplegic 7 (Smad7), which regulates TGF-β1 via negative feedback and mediates the interaction between TGF-β1 and other pathways." (PMID 35055013, 2022). "In addition, SMAD7, a negative modulator of TGF-β signalling, was found to be upregulated in VEGFA165 tumours." (PMID 22045186, 2011).
cancer (156 papers, 2003 to 2025). A tumor composed of atypical neoplastic, often pleomorphic cells that invade other tissues. "IL-6 and IL-22, two cytokines that activate STAT3, enhanced XIAP in cancer cells, and such induction was attenuated in SMAD7-deficient cells." (PMID 39001432, 2024). "Since its discovery, SMAD7 has been widely researched, especially to study its single nucleotide polymorphisms with cancer because of its possible signaling inhibition in the cell nucleus." (PMID 36607878, 2023). "On the other hand, increased expression of SMAD3, SMAD5, SMAD6, and SMAD7 was associated with low OS in stage I and II of the cancer." (PMID 37685308, 2023). "Among the Smad proteins regulated by JPHYD, we found that Smad7 is closely associated to miR-21-5p and Smad7 is downregulated in cancer tissues." (PMID 35518787, 2022). "SMAD7 is a key negative regulator of TGF-β signaling, it antagonizes TGF-β signaling through multiple mechanisms in the context of different cell types, and altered expression of SMAD7 is often associated with cancer, tissue fibrosis and inflammatory diseases." (PMID 35517795, 2022). "Previous studies have shown that SMAD7 is associated with the NF-κB pathway and therefore regulates the cell cycle in cancers." (PMID 33413425, 2021). "In fact, Smad7 suppression is associated with and resulted in Smad3 activation in inflammatory diseases including cancer." (PMID 34514726, 2021). "To date, a large number of studies have focused on the relationship between SMAD7 polymorphisms and cancer." (PMID 28070019, 2016). "For example, miR-21 and Smad7 are critical regulators of TGF-β1 signaling during the induction of carcinoma-associated fibroblast formation." (PMID 26968995, 2016). "Then in order to obtain the exact consequence of the relationship between SMAD7 rs12953717 polymorphism and cancer susceptibility, stratified analyses by ethnicity, study type, and cancer type were performed." (PMID 23472153, 2013). "The results indicated that SMAD7 rs12953717 was significantly associated with cancer risk in overall analysis." (PMID 23472153, 2013). "A comprehensive search was conducted to identify all eligible studies of SMAD7 rs12953717 polymorphism and cancer risk." (PMID 23472153, 2013). "We therefore performed a meta-analysis to clarify the association between the SMAD7 rs12953717 polymorphism and cancer risk." (PMID 23472153, 2013). "In the stratified analysis by ethnicity, we found that SMAD7 rs12953717 polymorphism was associated with increased cancer risk in both Caucasians and Asians." (PMID 23472153, 2013). "The association between SMAD7 rs12953717 and cancer risk was investigated in 14 studies with a total of 16928 cases and 14781 controls." (PMID 23472153, 2013). "To date, no meta-analysis has been conducted to investigate the association of rs12953717 polymorphism of SMAD7 gene and cancer risk." (PMID 23472153, 2013). "In the stratified analysis by cancer types, the results showed that SMAD7 rs12953717 polymorphism was significantly associated with increased colorectal risk." (PMID 23472153, 2013). "In the subgroup analysis by ethnicity, SMAD7 rs12953717 polymorphism was significantly associated with cancer risk in both Caucasians and Asians." (PMID 23472153, 2013). "Epidemiological studies of SMAD7 rs12953717 polymorphism, if large and unbiased, can provide insight into the in vivo relationship between the gene and cancer risk." (PMID 23472153, 2013). "In conclusion, our meta-analysis revealed that rs12953717 polymorphism of SMAD7 involved in the TGF-βsignaling pathway was significantly associated with cancer susceptibility." (PMID 23472153, 2013). "Based on these evidence‐based observations, Smad3 may play a pathogenic promoter in cancer, whereas Smad7 may be protective." (PMID 34514726, 2021). "Based on the hypothesis that SMAD7 deregulation is linked to several types of cancers, we aimed to perform a bibliometric analysis on SMAD7 research in the scope of oncology." (PMID 35252215, 2021).
cancer (continued). "A consistent body of evidence has linked Smad7 to several types of sporadic cancers." (PMID 31052449, 2019). "Because SMAD7 is an inhibitory SMAD that acts as a negative regulator of the TGF-β signaling pathway, it is logical that genetic polymorphisms of SMAD7 might impact susceptibility to cancer." (PMID 23472153, 2013). "Accumulating evidence has suggested that Mothers against decapentaplegic homolog 7 (SMAD7) rs12953717 polymorphism might be related to cancer risk." (PMID 23472153, 2013). "However, molecular epidemiological studies have yielded contradictory results concerning the potential role of SMAD7 rs12953717 polymorphism in cancer." (PMID 23472153, 2013). "Since the identification of SMAD7 rs12953717 polymorphism, an increasing number of studies suggested that SMAD7 rs12953717 polymorphism may play important roles in cancer development." (PMID 23472153, 2013). "We investigated the association between the SMAD7 rs12953717 polymorphism and cancer risk." (PMID 23472153, 2013). "However, studies focusing on the association of the SMAD7 rs12953717 polymorphism with cancer susceptibility had controversial conclusions." (PMID 23472153, 2013). "Genetic polymorphisms of genes that are involved in the TGF-β signaling pathways, including the mothers against decapentaplegic homolog 7 (SMAD7) gene, might impact susceptibility to cancer." (PMID 23472153, 2013). "Furthermore, Smad7 has been involved in colon carcinogenesis through complex and heterogeneous mechanisms, and Smad7 polymorphisms could influence cancer prognosis." (PMID 33920230, 2021). "The loss of SMAD7 could cause carcinoma cells more sensitive." (PMID 28467803, 2017). "Isolated studies have demonstrated that the knockout of PRMT5 in LC cells results in a decreased proliferation rate of cancer cells by disrupting the activity of the Smad7/STAT3 signaling axis." (PMID 39678513, 2024). "Thus, the loss of SMAD7 may render one more susceptible to carcinoma cells." (PMID 38275467, 2024). "miR-4775 overexpression in CRC promotes invasion, metastasis, and epithelial-mesenchymal transition (EMT) processes of cancer cells by activating SMAD7." (PMID 36969909, 2023). "Meanwhile, the activation of NF-κb by proinflammatory stimuli such as IL-1β was reported to inhibit TGF-β-induced gene expression by increasing the inhibitory Smad7 in hematopoietic progenitors and cancer cell lines." (PMID 37215126, 2023). "Whereas cancer cells infected with control adenovirus showed increased TGF-β/SMAD3 signaling activity in response to both rhTGF-β1 and MDA231-sEVs, this effect was dramatically impaired in SMAD7-overexpressing cancer cells." (PMID 38105247, 2023). "As result, exosomal miR-21-5p stimulates MMT of PMCs and increase cancer peritoneal diffusion via targeting SMAD7." (PMID 38081950, 2023). "The miR-484 is a key regulator in common cancers and non-cancer diseases, targeting inflammation, apoptosis, and mitochondrial function-related mRNAs (SMAD7, Fis1, YAP1, etc.), and plays an important role in fighting disease." (PMID 37504299, 2023). "Smad3-silence strategy is an enhanced immunotherapy in cancers, and targeting Smad3/Smad7 enhances NK cells’ functions in anti-cancer immunity." (PMID 36765396, 2023). "In HCC, SNHG6 upregulates ZEB1 expression by binding miR-101-3p and, in combination with downregulation of Smad7, induces epithelial–mesenchymal transition, speeding up cancer-cell metastasis." (PMID 40636922, 2023). "MiR-424-5p negatively regulates the expression of Smad7, while the Smad7 signal transduction pathway is known to promote the metastasis of advanced malignant tumors by participating in EMT." (PMID 35409396, 2022). "As an inhibitor of TGF-β signaling, SMAD7 is over-expressed in numerous cancer types and its abundance is positively correlated to the malignancy." (PMID 35954181, 2022). "A study by Yi Yu reported that SMAD7 maintains cell pluripotency and modulates cytokine-dependent regulation of cancer and inflammation." (PMID 34138687, 2021).